MIR129-2 (microRNA 129-2)
Synonyms: hsa-mir-129-2; MIR-129b; MIRN129-2; mir-129-2
Gene: MicroRNA gene on chromosome 11 (43,581,394 to 43,581,483, forward strand). Ensembl gene ENSG00000199077.
Gene Ontology:
Biological process: miRNA-mediated post-transcriptional gene silencing
Cellular component: RISC complex
Homologues: Orthologues: chimpanzee ptr-mir-129-2 (100% identical), guinea pig MIR129-2 (96% identical), rabbit MIR129-2 (96% identical), macaque mml-mir-129-2 (94% identical), pig MIR129-2 (94% identical), tropical clawed frog xtr-mir-129-1 (88% identical), zebrafish mir129-2b (87% identical), zebrafish dre-mir-129-2 (82% identical), dog MIR129-2 (69% identical), mouse Mir129b (47% identical). Paralogues in human: MIR129-1 (67% identical).
Diseases named in the same sentence as MIR129-2 in open-access papers:
MIR129-2 is named in the same sentence as 1 disease in open-access papers, as found by Europe PMC text mining. Sharing a sentence is not in itself a finding about the gene and the disease. The quoted sentences say what the papers report.
breast carcinoma (1 paper, 2021). "Downregulation of MIR129-2 by promoter hypermethylation induced breast cancer cell proliferation and apoptosis." (PMID 33403044, 2021).